CSTF3 (cleavage stimulation factor subunit 3)
Description:
One of the multiple factors required for polyadenylation and 3'-end cleavage of mammalian pre-mRNAs.
Synonyms: CstF-77
Tractability: PROTAC: ubiquitination databases record sites on it; its protein half-life has been measured.
Gene: Protein-coding gene on chromosome 11 (33,077,188 to 33,162,371, reverse strand). Ensembl gene ENSG00000176102.
Subcellular location: Nucleus
Subcellular location (Human Protein Atlas): Nucleoplasm
Pathways (Reactome):
Metabolism of RNA: Processing of Intronless Pre-mRNAs; mRNA 3'-end processing; mRNA Polyadenylation
Disease: Dengue Virus-Host Interactions
Gene expression (Transcription): RNA Polymerase II Transcription Termination
Gene Ontology:
Molecular function: protein binding; RNA binding
Biological process: co-transcriptional mRNA 3'-end processing, cleavage and polyadenylation pathway; regulation of mRNA 3'-end processing; mRNA 3'-end processing; RNA processing
Cellular component: mRNA cleavage stimulating factor complex; nucleoplasm; nucleus
Genetic constraint (gnomAD): Loss-of-function variants: 15 observed, 61.35 expected, observed/expected ratio (o/e) 0.24, 90% interval 0.16 to 0.38. The upper end of that interval is the gene's LOEUF score, 0.38, which puts it in group 1 of 6, group 1 being the genes least tolerant of losing a copy. Missense variants: 262 observed, 644.26 expected, observed/expected ratio (o/e) 0.41, 90% interval 0.37 to 0.45. Synonymous variants: 196 observed, 212.7 expected, observed/expected ratio (o/e) 0.92, 90% interval 0.82 to 1.04.
Homologues: Orthologues: chimpanzee CSTF3 (100% identical), macaque CSTF3 (100% identical), dog CSTF3 (99% identical), pig CSTF3 (99% identical), guinea pig CSTF3 (99% identical), rabbit CSTF3 (99% identical), mouse Cstf3 (99% identical), rat Cstf3 (99% identical), tropical clawed frog cstf3 (94% identical), zebrafish cstf3 (91% identical), Drosophila melanogaster su(f) (58% identical), Caenorhabditis elegans suf-1 (50% identical).
Diseases named in the same sentence as CSTF3 in open-access papers:
CSTF3 is named in the same sentence as 8 diseases in open-access papers, as found by Europe PMC text mining. Sharing a sentence is not in itself a finding about the gene and the disease. The quoted sentences say what the papers report.
gastric cancer (1 paper, 2024). A primary or metastatic malignant neoplasm involving the stomach. "In addition, CSTF3 was upregulated in 5-fluorouracil (5-FU)-sensitive gastric cancer (GC) cell lines and could be used as a biomarker of 5-FU for GC patients." (PMID 38898019, 2024).
triple-negative breast carcinoma (1 paper, 2024). An invasive breast carcinoma which is negative for expression of estrogen receptor (ER), progesterone receptor (PR), and human epidermal growth factor receptor 2 (HER2). "CSTF3 was upregulated in triple-negative breast cancer (TNBC) cells, and CSTF3 promoted the proliferation of TNBC by inducing APA of NRAS and c-JUN." (PMID 38898019, 2024).
cancer (4 papers, 2018 to 2024). A tumor composed of atypical neoplastic, often pleomorphic cells that invade other tissues. "Similarly, increased CstF-77/CSTF3 has been associated with alternative 3′ end processing in cancer." (PMID 30257008, 2018). "In the first enriched pathway, surveillance pathway, five genes (HBS1L, DAZAP1, RBM8A, CSTF3, and CSTF2T) overlap, all of which have been previously implicated in cancer progression." (PMID 38305998, 2024). "Significantly, disturbance of CSTF3 expression affects global mRNA 3′UTR length, protein expression and cell functions, which have been closely associated with the chemotherapy-sensitivity and progression of some cancers." (PMID 38898019, 2024). "To date, relatively few reports have been acquired on CSTF3 for many diseases and cancer research." (PMID 38898019, 2024). "However, how CPSF2 and CSTF3 regulate the stability of DLGAP1-AS2 is not clear, and whether the regulatory mechanism could be validated in other cancer types also remains to be elucidated." (PMID 36376892, 2022).
tumor (3 papers, 2020 to 2022). "In B-cell leukemia/lymphoma samples CSTF3 protein is expressed at significantly higher levels in tumours is associated with 3′UTR shortening." (PMID 32560344, 2020). "Analyses of public CRC databases revealed that both CPSF2 and CSTF3 were upregulated in tumor tissues compared with paired NCTs, and higher CPSF2 and CSTF3 expression was associated with worse survival." (PMID 36376892, 2022). "In contrast, in triple-negative breast cancer tumours 3′UTR shortening correlating with elevated expression of CSTF3 has been observed." (PMID 32560344, 2020).
CSTF3 also shares sentences with these, for which no sentence is quoted: Aphasia (1 paper); Autoimmunity (1); epilepsy (1); ovarian carcinoma (1).